TATDN3 (TatD DNase domain containing 3)
Description:
Exhibits 3'-exonuclease and apurinic/apyrimidinic (AP) endonuclease activities (in vitro). Show preferential AP endonuclease activity on double-stranded DNA substrates and 3'-exonuclease activity on single-stranded DNA.
Tractability: PROTAC: ubiquitination databases record sites on it; its protein half-life has been measured.
Gene: Protein-coding gene on chromosome 1 (212,791,828 to 212,816,830, forward strand). Ensembl gene ENSG00000203705.
Subcellular location: Nucleus
Subcellular location (Human Protein Atlas): Nucleoplasm; Focal adhesion sites; Golgi apparatus
Gene Ontology:
Molecular function: DNA-(apurinic or apyrimidinic site) endonuclease activity; single-stranded DNA 3'-5' DNA exonuclease activity; hydrolase activity, acting on ester bonds
Cellular component: mitochondrion; nucleus
Genetic constraint (gnomAD): Loss-of-function variants: 18 observed, 23.67 expected, observed/expected ratio (o/e) 0.76, 90% interval 0.52 to 1.13. The upper end of that interval is the gene's LOEUF score, 1.13, which puts it in group 4 of 6, group 1 being the genes least tolerant of losing a copy. Missense variants: 237 observed, 240.55 expected, observed/expected ratio (o/e) 0.99, 90% interval 0.88 to 1.1. Synonymous variants: 81 observed, 91.74 expected, observed/expected ratio (o/e) 0.88, 90% interval 0.74 to 1.06.
Homologues: Orthologues: chimpanzee TATDN3 (99% identical), macaque TATDN3 (97% identical), pig TATDN3 (91% identical), rabbit TATDN3 (91% identical), dog TATDN3 (91% identical), rat AABR07022144.1 (87% identical), mouse Tatdn3 (85% identical), guinea pig TATDN3 (74% identical), tropical clawed frog tatdn3 (73% identical), zebrafish TATDN3 (67% identical), Caenorhabditis elegans B0432.8 (38% identical). Paralogues in human: TATDN2 (22% identical), TATDN1 (21% identical).